MAL2 (mal, T cell differentiation protein 2)
Diseases named in the same sentence as MAL2 in open-access papers (continued):
Sharing a sentence is not in itself a finding about the gene and the disease.
breast tumor (4 papers, 2021 to 2024). "MAL2 depletion in a mice xenograft suppressed breast tumor growth and enhanced tumor-infiltrating CD8 + T cells cytotoxicity, presumably by facilitating tumor antigen presentation." (PMID 38769215, 2024). "Reduction of MAL2 in breast tumor cells can enhance CD8+ T cell-mediated cytotoxicity and inhibit the growth of breast tumors." (PMID 34567213, 2021). "In conclusion, our work demonstrates for the first time that in breast tumors NSMCE2 and MAL2 can be dysregulated by SEs, are frequently amplified, and thus, overexpressed." (PMID 36224576, 2022).
meningioma (4 papers, 2013 to 2023). A generally slow growing tumor attached to the dura mater. "Thus, suppression of MAL2 gene expression is tightly associated with malignancy of meningiomas." (PMID 23349797, 2013). "A similar case is that of meningioma, in which MAL2 was found to be strongly expressed in benign tumors, but silenced in malignant tumors; this is an example of de novo silencing by DNA methylation." (PMID 37345137, 2023). "For MAL2, noteworthy, previous studies reported promotor hypermethylation and downregulation in high-grade and recurrent meningiomas." (PMID 35445910, 2022). "As previous reports already demonstrated expression in meningiomas and correlation with histology by microarray analyses and gene arrays, immunohistochemical slides for MAL2 and LMO3 were subjected to interim analyses." (PMID 35445910, 2022). "For MAL2, all 52 analyzed cases including 32 benign and 20 high-grade meningiomas displayed immunopositivity with strong expression (median 6, range 1–12) in most (N = 45) cases." (PMID 35445910, 2022). "Promoter methylation of MEG3, GSTP1, and MAL2 has been shown to more commonly in higher grade meningiomas." (PMID 33194703, 2020). "In meningiomas, three previous studies analyzed MAL2 and LMO3 expression." (PMID 35445910, 2022). "To further support our analysis, we examined a publicly available gene expression array data for meningiomas, and found significantly suppressed MAL2 gene expression in recurrent malignant samples compared to benign samples (P = 0.0096, two-tailed unpaired t-test)." (PMID 23349797, 2013). "However, in an IHC study, MAL2 was detected in both benign and malignant meningiomas." (PMID 37345137, 2023). "Expression of the corresponding onco- and tumor suppressor genes TRIM58, FAM84B, ELOVL2, MAL2, LMO3, and DIO3 were analyzed and scored by immunohistochemical staining and RT-PCR in samples of 111 meningioma patients." (PMID 35445910, 2022). "Recent in vitro analyses revealed a dose-dependent efficiency of DCT also in high-grade meningiomas, with specific DNA demethylation of several onco- or tumor suppressor genes (TRIM58, FAM84B, ELOVL2, MAL2, LMO3, DIO3), which have been hardly investigated in meningiomas yet." (PMID 35445910, 2022).
lung carcinoma (3 papers, 2022 to 2023). "Study have shown that high expression of MAL2 facilitates the proliferation of lung cancer cells in vitro and in vivo." (PMID 37480012, 2023). "Dysregulation of T cell differentiation protein 2 (MAL2) has been observed in multiple cancers, but its exact role in lung cancer is poorly understood." (PMID 35437691, 2022). "Further studies are needed to understand the mechanistic details of MAL2-mediated augmentation of ribosome synthesis in lung cancer." (PMID 35437691, 2022). "Other stronger correlations were that of MAL (LUAD) and MYADM (LUSC) in lung cancer, which was the second most highly ranked in the 2020 ranking, with 12.5% of the new cancer cases, and that of MAL2 and MALL in PAAD, which was ranked twelfth, with 2.7% of the new cases." (PMID 37345137, 2023). "An effect of MAL2 silencing on cell proliferation, similar to that in lung cancer cell lines, was observed in breast, ovarian, pancreatic and prostate cancer cell lines, in which migration and invasion and the epithelial-to-mesenchymal transition were decreased." (PMID 37345137, 2023). "The biological role of MAL2 in lung cancer cells was investigated both in vitro and in vivo." (PMID 35437691, 2022). "MAL2 signal was obviously stronger in lung cancer tissues compared with peritumoral tissues." (PMID 35437691, 2022). "Here, MAL2 was identified to be significantly upregulated in NSCLC tissues, and its high expression correlated with poor outcomes in lung cancer patients." (PMID 35437691, 2022). "Here, we observed that MAL2 was overexpressed in NSCLC and promoted lung cancer growth." (PMID 35437691, 2022). "However, no study to date has examined whether MAL2 expression is increased in lung cancer, or its potential clinical significance." (PMID 35437691, 2022).
triple-negative breast carcinoma (3 papers, 2023 to 2025). An invasive breast carcinoma which is negative for expression of estrogen receptor (ER), progesterone receptor (PR), and human epidermal growth factor receptor 2 (HER2). "In our study, MAL2 overexpression was associated with shorter survival in triple-negative breast cancer." (PMID 38769215, 2024). "MAL2 is overexpressed in TNBC, and high MAL2 expression predicts shorter overall survival in triple-negative breast cancer in both the TMA and TCGA cohorts." (PMID 38769215, 2024). "To examine the predictive value of MAL in patients with triple-negative breast cancer, we dichotomized the samples into low and high MAL2 expression groups, with the cutoff point set at 88 H-score." (PMID 38769215, 2024). "Results showed that KK-CL-1 can regulate the malignant biological behaviors of triple-negative breast cancer via the MAL2/MUC1-C/PI3K/AKT/mTOR pathway." (PMID 36895039, 2023). "KK-LC-1 promotes the malignant biological behavior of triple-negative breast cancer cells via the MAL2/MUC1-C/PI3K/AKT/mTOR pathway." (PMID 36895039, 2023). "Based on these results, we can conclude that KK-LC-1 regulates the biological characteristics of triple-negative breast cancer cells through the MAL2/MUC1-C/PI3K/AKT/mTOR pathway." (PMID 36895039, 2023). "Taken together, we speculated that KK-LC-1 may regulate the biological characteristics of triple-negative breast cancer via the MAL2/MUC1-C/PI3K/AKT pathway." (PMID 36895039, 2023). "Besides, Z839878730 has little tumor-killing effect on human normal mammary epithelial cells MCF10A and can inhibit the malignant biological behaviors of triple-negative breast cancer cells by MAL2/MUC1-C/PI3K/AKT/mTOR pathway." (PMID 36895039, 2023). "Therefore, we conclude that KK-LC-1 regulates the biological characteristics of triple-negative breast cancer cells through the MAL2/MUC1-C/PI3K/AKT/mTOR pathway." (PMID 36895039, 2023). "Based on the literature and sequencing results of this study, we speculated that KK-LC-1 may regulate the biological characteristics of triple-negative breast cancer cells through the MAL2/MUC1-C/PI3K/AKT/mTOR pathway." (PMID 36895039, 2023). "In triple-negative breast cancer (TNBC), overexpression of MAL2 promotes endocytosis, leading to resistance to novel therapeutic agents." (PMID 40666073, 2025). "Further in vitro experiments also found that Z8 has a low EC50 and can inhibit the malignant biological behaviors of KK-LC-1 high expressed triple-negative breast cancer cells MDA-MB-231 and MDA-MB-468 by MAL2/MUC1-C/PI3K/AKT/mTOR pathway." (PMID 36895039, 2023). "To further validate the relationships between KK-LC-1, MAL2, and MUC1 expression, we detected the expression of KK-LC-1, MAL2, and MUC1 in 126 triple-negative breast cancer clinical samples." (PMID 36895039, 2023). "We found that KK-LC-1 expression was significantly positively correlated with MAL2 and MUC1 expression in 126 triple-negative breast cancer specimens." (PMID 36895039, 2023). "To further explore if Z8 can also influence the pathway of MAL2/MUC1-C/PI3K/AKT/mTOR, we treatment MDA-MB-231 and MDA-MB-468 triple-negative breast cancer cell lines with Z839878730." (PMID 36895039, 2023). "High MAL2 predicts unfavorable prognosis in triple-negative breast cancer, and its expression is independent of PD-1 levels and clinicopathological features of TNBC." (PMID 38769215, 2024).
cholangiocarcinoma (2 papers, 2020 to 2023). A carcinoma that arises from the intrahepatic biliary tree (intrahepatic cholangiocarcinoma) or from the junction, or adjacent to the junction, of the right and left hepatic ducts (hilar cholangiocarcinoma). "More puzzling are the cases of malignant liver hepatocellular carcinoma (LIHC), cholangiocarcinoma (CHOL), and renal cell carcinoma, in which, MAL2 was shown by IHC to be downregulated relative to benign tumors, but upregulated in cholangiocarcinoma in another study." (PMID 37345137, 2023).
COVID-19 (2 papers, 2023). A disease caused by infection with severe acute respiratory syndrome coronavirus 2. "Secondly, we showed that the density of the lipid raft protein MAL (and potentially MAL2) is augmented in light-density sucrose gradient fractions from human SAECs challenged with pEVs from COVID-19 patients compared to those from non-COVID-19 patients." (PMID 36675169, 2023).
glioma (2 papers, 2023 to 2024). A benign or malignant brain and spinal cord tumor that arises from glial cells (astrocytes, oligodendrocytes, ependymal cells). "The MAL2 methylation-based diagnostic model has the potential to aid in the early diagnosis of glioma." (PMID 38831979, 2024). "The candidate MAL2 CpG sites were validated by pyrosequencing and used to construct a diagnostic model for glioma." (PMID 38831979, 2024). "Additionally, a risk score model was built based on MAL2 methylation to assess the prognosis of glioma." (PMID 38831979, 2024). "The risk score model based on MAL2 methylation could provide valuable information for evaluating the prognosis of glioma patients." (PMID 38831979, 2024). "Owing to the extremely low expression of MAL2, it is challenging to define the cutoff value of the diagnostic model to distinguish glioma, as minor experimental errors might lead to a marked reduction in diagnostic accuracy." (PMID 38831979, 2024). "As expected, glioma patients with low methylation in MAL2 cg02225716 (cg1) and cg06822816 (cg7) in the TCGA database had longer OS (P < 0.0001)." (PMID 38831979, 2024). "Survival analysis was also conducted to determine the relationship between highly methylated MAL2-specific CpG sites and the prognosis of glioma." (PMID 38831979, 2024). "Kaplan–Meier (KM) analysis showed that glioma patients with high expression of MAL2 tended to have longer overall survival (OS) in the TCGA database." (PMID 38831979, 2024). "Therefore, the methylation levels of all known MAL2 CpG sites of diverse tissues in TCGA were plotted, and MAL2 cg06822816 (cg7) was selected based on its differential methylation in gliomas versus other cancers." (PMID 38831979, 2024). "The receiver operating characteristic curve (ROC) of The Cancer Genome Atlas (TCGA) and Genotype-Tissue Expression Project (GTEx) databases revealed that glioma could be distinguished from normal brain tissues by MAL2 expression." (PMID 38831979, 2024). "This study aimed to investigate the potential of MAL2 as a biomarker for glioma." (PMID 38831979, 2024). "Overall, the findings indicated that MAL2 could serve as a biomarker for glioma patient diagnosis and prognosis evaluation to improve patient outcomes." (PMID 38831979, 2024). "This indicated that MAL2 methylation levels might exert a certain impact on the prognosis of glioma patients." (PMID 38831979, 2024). "The findings also showed that MAL2 was more highly methylated in glioma than in other cancers." (PMID 38831979, 2024). "Then, glioma, nonglioma tumor, and nontumor samples from Huashan Hospital were pyrosequenced for these selected MAL2 CpG sites." (PMID 38831979, 2024). "There were clear significant differences in glioma and nonglioma samples at the nine selected MAL2 CpG sites." (PMID 38831979, 2024). "However, in both lower-grade glioma (LGG) and glioblastoma (GBM), MAL2 was significantly down-regulated." (PMID 38831979, 2024).
lung adenocarcinoma (2 papers, 2021 to 2022). A carcinoma that arises from the lung and is characterized by the presence of malignant glandular epithelial cells. "We extended this analysis to two additional lung adenocarcinoma cell lines, NCI-H23 and CRL-5872, and found that MAL2 overexpression resulted in an increased cell proliferation similar to observed in A549 MAL2 expressing cells." (PMID 35437691, 2022).
non-small cell lung carcinoma (2 papers, 2022 to 2023). A group of at least three distinct histological types of lung cancer, including non-small cell squamous cell carcinoma, adenocarcinoma, and large cell carcinoma. "MAL2 silencing in non-small cell lung cancer cells decreased cell proliferation in vitro, whereas MAL2 overexpression had the opposite effect, and increased tumor size in xenografts in nude mouse models." (PMID 37345137, 2023).
pancreatic adenocarcinoma (2 papers, 2021 to 2023). "MAL2 is upregulated in multiple human cancers relative to normal tissues and in cancer-derived cell lines, including BRCA, pancreatic adenocarcinoma (PAAD), HNSC, COAD-READ, ovarian cancer (OV), STAD, uterine corpus endometrial cancer (UCEC), mesothelioma and neuroblastoma." (PMID 37345137, 2023).
pancreatic ductal adenocarcinoma (2 papers, 2021 to 2022). An infiltrating adenocarcinoma that arises from the epithelial cells of the pancreas. "For MAL2, we found that, while high gene expression is linked to shorter survival in 4 cancer types (pancreatic ductal adenocarcinoma, uveal melanoma, thymoma and uterine corpus endometrial carcinoma), it is linked to better survival in bladder urothelial and head and neck squamous cell carcinoma." (PMID 36224576, 2022).
prostate carcinoma (2 papers, 2009 to 2022). A carcinoma that arises from epithelial cells of the prostate gland. "MAL2 has also been reported to be distributed in both lipid raft and non-raft fractions in primary thyrocytes and PC-3 prostate carcinoma cells, predicting additional, uncharacterised cellular functions for MAL2 outside lipid rafts." (PMID 19175940, 2009).
serous carcinomas (2 papers, 2010 to 2025). "High-level MAL2 expression was also noted in mucinous, clear cell and endometrioid ovarian carcinomas, albeit less frequently than in serous carcinomas." (PMID 20846453, 2010). "High-level MAL2 staining was most frequent in serous carcinomas (102/182, 56%), followed by mucinous (5/10, 50%), clear cell (3/8, 38%) and endometrioid subtypes (6/20, 30%), and serous carcinomas also displayed the highest median MAL2 SPC." (PMID 20846453, 2010). "MAL2 expression was highest in serous carcinomas relative to other histological subtypes, whereas TPD52 expression was highest in clear cell carcinomas." (PMID 20846453, 2010). "Dividing the stage III serous carcinoma cohort according to median MAL2 or TPD52 SPC tumour values indicated similar overall survival according to MAL2 staining, but a trend towards improved overall survival with increased TPD52 staining." (PMID 20846453, 2010). "Statistical comparisons reproducibly highlighted that MAL2 staining was higher in high-grade serous carcinomas, whereas TPD52 was indicated to be more equivalently expressed." (PMID 20846453, 2010). "MAL2 was significantly overexpressed in high-grade serous carcinomas compared with borderline tumours, and in high-grade serous carcinomas relative to the remaining histological subtypes combined." (PMID 20846453, 2010). "As MAL2 was most frequently overexpressed in serous carcinomas, we compared MAL2 and TPD52 staining in high-grade serous carcinomas versus all others." (PMID 20846453, 2010). "In the case of both proteins, more low-grade serous carcinoma (grade 1) showed high-level cytoplasmic staining compared with serous borderline tumours, however this only reached statistical significance for visual scoring of MAL2 staining." (PMID 20846453, 2010). "Like MAL2, TPD52 was overexpressed in high-grade serous carcinomas relative to borderline tumours, but was more equivalently expressed in high-grade serous tumours relative to the combined cohort of other histological subtypes." (PMID 20846453, 2010). "MAL2 and TPD52 were significantly overexpressed in high-grade serous carcinomas compared with serous borderline tumours." (PMID 20846453, 2010).
Alzheimer disease (1 paper, 2024). A progressive, neurodegenerative disease characterized by loss of function and death of nerve cells in several areas of the brain leading to loss of cognitive function such as memory and language. "Mal2 is involved in glutamatergic neurotransmission and is downregulated in the brains of patients suffering from Alzheimer’s disease." (PMID 38891920, 2024).
benign meningioma (1 paper, 2013). A grade I, slowly growing meningioma. "Examination of expression data of genes with hypermethylated promoter CpG islands also identified one gene, MAL2, with high expression levels in the benign meningiomas but low expression in malignant tumors." (PMID 23349797, 2013).
cervical cancer (1 paper, 2021). A primary or metastatic malignant neoplasm involving the cervix. "MAL2 has been reported to be highly expressed in several types of epithelial tumors, such as cervical cancer, and is related to cell invasion and metastasis." (PMID 35111745, 2021).
colon cancer (1 paper, 2021). "Besides, it was reported that MAL2 expression increased in colon cancer tissues and lymph nodes with metastasis with high accuracy and specificity in the diagnosis of colon cancer." (PMID 34567213, 2021).
cystadenoma (1 paper, 2010). A benign or borderline cystic epithelial neoplasm arising from the glandular epithelium. "Comparisons of MAL2 and TPD52 expression were also made in a smaller cohort of mucinous carcinomas, borderline tumours and cystadenomas." (PMID 20846453, 2010).
diabetes type 2 (1 paper, 2023). "A computational analysis of transcriptomic data showed MAL2 to be one of the strongest hub genes involved in signaling pathways in diabetes type 2 connected to tuberculosis and rheumatoid arthritis, although the contribution (if any) of MAL2 to the disease is unknown." (PMID 37345137, 2023).
endometrioid carcinomas (1 paper, 2010). "High-level MAL2 staining was significantly more frequent and MAL2 SPCs were significantly higher in serous than endometrioid carcinomas." (PMID 20846453, 2010).
gallstones (1 paper, 2018). Solid crystalline precipitates in the biliary tract, usually formed in the gallbladder, resulting in the condition of cholelithiasis. "Three novel gallstone-associated non-coding variants at the LITAF and MAL2 loci and a stop gained variant at the FUT2 locus are correlated with (r2 > 0.8) or represent the strongest cis-eQTLs in their respective regions." (PMID 30504769, 2018).
influenza (1 paper, 2020). An acute viral infection of the respiratory tract, occurring in isolated cases, in epidemics, or in pandemics; it is caused by serologically different strains of viruses (influenzaviruses) designated A, B, and C, has a 3-day incubation period, and usually lasts for 3 to 10 days. "Mal2, a paralog of Mal, was also found to be 9-fold downregulated (p = 1.9 × 10−15) in RNA-seq data from E7.5 influenza-inoculated fetal thymuses compared to controls." (PMID 32911797, 2020). "By RT-qPCR, Mal2 tended to be decreased in influenza-inoculated fetal thymic RNA in Experiment 1 (p = 0.1) and was decreased in Experiment 2 (p = 0.05) compared to controls." (PMID 32911797, 2020).
liver cancer (1 paper, 2023). An epithelial or non-epithelial malignant neoplasm that arises from the liver. "In liver cancer, a study has shown that MAL2 is associated with early stage HCC rather than late stage." (PMID 37958451, 2023). "Interestingly, a significant tendency for co-occurrence between IL7 and MAL2 was only found amongst the top ten upregulated genes in the TCGA liver cancer database (p < 0.001)." (PMID 37958451, 2023).